SMAD1 (SMAD family member 1)
Diseases named in the same sentence as SMAD1 in open-access papers (continued):
Sharing a sentence is not in itself a finding about the gene and the disease.
myeloma (10 papers, 2015 to 2024). "Multiple myeloma cells are sensitive to BMP- and activin-induced apoptosis via activated SMAD1/5/8 transcription factors that cause downregulation of the c-MYC oncogene, followed by Bcl-xL downregulation and caspase 3 cleavage." (PMID 36717825, 2023). "We here show that FK506 potentiated BMP-induced SMAD1/5/8-activation and apoptosis in multiple myeloma cells, likely by sequestering FKBP12." (PMID 36717825, 2023). "Taken together, FK506 potentiates BMP- and activin-induced SMAD1/5/8 activation and apoptosis in multiple myeloma cells." (PMID 36717825, 2023). "Both BMP9 and BMP10 induce growth arrest and/or apoptosis in multiple myeloma cells in a SMAD1/5/8-dependent manner." (PMID 37095146, 2023). "We demonstrate that SMAD1 is highly expressed in myeloma cells of MM patients with advanced stages or relapsed disease, and is associated with significantly shorter progression-free and overall survivals." (PMID 34134766, 2021). "We have shown that BMPs induce growth arrest and/or apoptosis in myeloma cells via activation of the SMAD1/5 pathway which in turn leads to c-MYC downregulation." (PMID 32235336, 2020). "We showed that activin A and activin B likely signal through endogenous wildtype ALK2 to activate SMAD1/5 in myeloma and hepatocellular cell lines and the present study further supports this finding." (PMID 32235336, 2020). "The role of BMPR2 as an inhibitor of Activin-SMAD1/5/8 signaling was recently shown in myeloma cells." (PMID 31826007, 2019). "We have previously shown that BMPs mediated growth arrest and apoptosis in myeloma cells by activation of SMAD1/5/8 and consequent downregulation of MYC." (PMID 26047946, 2015). "We wanted to study the impact of activin A on SMAD1/5/8-signaling and, hence, on myeloma cell growth and survival." (PMID 26047946, 2015). "FK506 potentiated BMP-induced SMAD1/5/8 activation and apoptosis in multiple myeloma cell lines." (PMID 36717825, 2023). "In multiple myeloma cells, activation of SMAD1/5/8 leads to apoptosis." (PMID 36717825, 2023). "We here aimed to increase myeloma cell death by enhancing SMAD1/5/8 activity." (PMID 36717825, 2023). "SMAD1 silencing also enhanced the sensitivity of resistant MM cells to anti-myeloma drug BTZ." (PMID 34134766, 2021). "The underlying mechanism of ActivinA/SMAD1/5 signaling is not fully understood but suggests ACVR1 dependency and independency of ACVR1B/C/TGFBR1 as demonstrated by inhibitor experiments in FOP iECs being in line with knockdown studies in FOP and myeloma cells." (PMID 33410098, 2021). "Whether SMAD1 plays an important role in multiple myeloma (MM) pathogenesis and can serve as a therapeutic target are largely unknown." (PMID 34134766, 2021). "Our results also indicate that DM is a potent anti-myeloma agent by inhibiting SMAD1 phosphorylation and may provide novel therapeutic strategies to treat MM." (PMID 34134766, 2021). "In recent work, it was observed that activin A and B could signal through wild-type ACVR1 in myeloma cells, activating the SMAD1/5/8 signalling pathway and inducing myeloma cell death." (PMID 31683698, 2019). "BMP-induced apoptosis in myeloma cell lines is dependent on SMAD1/5/8-phosphorylation." (PMID 26047946, 2015). "Therefore, it was proposed that a reduction in BMPR2 levels could increase ACVR1 complex formation with ACVR2A or ACVR2B, thus enhancing ACVR1-mediated SMAD1/5/8 signalling and myeloma cell death." (PMID 31683698, 2019). "Here we show that the immunosuppressive drug FK506 potentiated SMAD1/5/8-activation via the TGF-β/BMP type I receptor ALK2, and thereby increased myeloma cell death." (PMID 36717825, 2023). "Having established that FK506 potentiated BMP6-induced SMAD1/5/8-activation and apoptosis in INA-6 cells, we next wanted to see how common this was among myeloma cell lines." (PMID 36717825, 2023).
myeloma (continued). "Multiple myeloma cell lines were treated with FK506, or other FKBP-binding compounds, combined with different BMPs before analyzing SMAD1/5/8 activity and cell viability." (PMID 36717825, 2023). "We have previously shown that activin A and activin B activated SMAD1/5 via ALK2 and induced cell death in IH-1 and INA-6 myeloma cell lines." (PMID 32235336, 2020). "In myeloma cells, BMP-6- and BMP-9-induced activation of SMAD1/5/8 through ACVR2A/ACVR2B/ALK2 was inhibited by activin A treatment." (PMID 26047946, 2015). "Knockdown of BMPR2 caused potentiation of activin-induced SMAD1/5, but not SMAD2/3, activity in multiple myeloma and hepatocytic carcinoma cells." (PMID 32235336, 2020). "We found that recombinant human GDF15 activated SMAD2, but not SMAD1/5 in the multiple myeloma cell line IH-1." (PMID 29161287, 2017).
colorectal cancer (9 papers, 2011 to 2025). A primary or metastatic malignant neoplasm that affects the colon or rectum. "Inactivation of BMPR1A, BMPR2, and SMAD4 was frequently observed in sporadic colorectal cancer, correlating to loss of Smad1/5/8 phosphorylation." (PMID 22072987, 2011). "This study claimed that low expression of SMAD1 in colorectal cancer was related to prognosis and immune cell infiltration, but SMAD1 protein was significantly increased in colorectal cancer tissues." (PMID 36969909, 2023). "In the present study, we demonstrate that Smad1 induces the expression of Ajuba and Snail to promote cell migration in colorectal cancer cells." (PMID 29299158, 2017). "In this paper, we demonstrate that Smad1 promotes cell migration of colorectal cancer cells by upregulating Snail and Ajuba." (PMID 29299158, 2017). "Here, we demonstrate that Smad1 promotes migration of colorectal cancer (CRC) cells by inducing Snail and Ajuba expression simultaneously, but no apparent effect on Twist1 expression." (PMID 29299158, 2017). "To define the signaling pathways that mediate Dragon action on colorectal cancer cell proliferation, we analyzed Smad1/5/8, AKT, Erk1/2 and p38 phosphorylation levels in the stable Dragon knockdown CT26.WT and CMT93 mouse cells." (PMID 26029998, 2015). "Moreover, the expression of Ajuba and Smad1 in colorectal cancer are positively correlated, suggesting that Smad1 and Ajuba may be potential therapeutic targets and prognostic factors for CRC." (PMID 29299158, 2017). "In conclusion, B7-H3 promotes the EMT in colorectal cancer cells by activating the PI3K-Akt pathway and upregulating the expression of Smad1." (PMID 27145365, 2016). "Additionally, Smad1 is upregulated by B7-H3 via PI3K-Akt pathway and promotes Epithelial-Mesenchymal Transition (EMT) process in the colorectal cancer cells." (PMID 29299158, 2017).
glioblastoma (9 papers, 2012 to 2025). The most malignant astrocytic tumor (WHO grade IV). "Our results established that glioblastoma cells undergo endothelialisation in response to TGF-β-Smad1/5 signaling activation." (PMID 39724753, 2024). "After confirming TGF-β-Smad1/5 signalling activation in the lattice forming glioblastoma cell lines, we sought to specifically inhibit this molecular pathway to investigate its functional relevance on tumour cell endothelialisation." (PMID 39724753, 2024). "We report that TGF-β-mediated Smad1/5 activation in glioblastoma cells regulates tumour cell transdifferentiation into an endothelialised phenotype." (PMID 39724753, 2024). "Having established TGF-β-Smad1/5 signaling as the key molecular mechanism driving endothelialisation in glioblastoma, we next sought to define its functional relevance for tumour progression." (PMID 39724753, 2024). "Strikingly, glioblastoma tumour cells have also been described to increase Smad1/5 phosphorylation in response to TGF-β, an effect previously thought to be specific to endothelial cells." (PMID 39724753, 2024). "Surprisingly, Smad1 gene knockdown in human LN18 glioblastoma cells seriously resulted in their cell death." (PMID 34357080, 2021). "Our findings provide new insights into the understanding and elucidation of autocrine role of BMP7 and Smad1/5 signaling in promoting the glioblastoma metastasis." (PMID 34357080, 2021). "The pro-differentiated role of BMPs/Smad1 in NSCs and glioblastoma cell lines has inspired investigators to further study their roles in hGSCs." (PMID 26908439, 2016). "Although increased Smad1/5 activity has been described in glioblastoma tumour cells treated with TGF-β, the role played by ALK1 remained unknown." (PMID 39724753, 2024). "Here, we hypothesize that TGF-β-Smad1/5 signaling activation drives glioblastoma progression by regulating the development and expansion of the abnormal vasculature observed in glioblastomas." (PMID 39724753, 2024). "Although activation of TGF-β-Smad1/5 signaling in endothelial cells promotes angiogenesis, the precise role played by this molecular pathway in glioblastoma cells remains unknown." (PMID 39724753, 2024). "Similarly, our results showed that targeting TGF-β-Smad1/5 signaling activity impaired the endothelialisation of glioblastoma tumour cells." (PMID 39724753, 2024). "Thus, we cannot identify the Smad1 role in p75NTR upregulation of BMP7 stimulation in human LN18 glioblastoma cells." (PMID 34357080, 2021). "Moreover, our data also accidently found the Smad1 potential role in maintaining the glioblastoma cell survival since its gene knockdown resulted in the cell death." (PMID 34357080, 2021). "Thus, our findings open a new avenue to improve the survival of glioblastoma patients as reduced endothelialisation may be achieved by therapies targeting TGF-β-Smad1/5 signaling." (PMID 39724753, 2024). "Thus, targeting Smad1/5 activity may be a novel and effective therapeutic strategy to ameliorate glioblastoma progression as demonstrated in this study via treatment with Ad-Smad6." (PMID 39724753, 2024). "Moreover, our present study also suggests that the interesting data about Smad1 gene knockdown in human LN18 glioblastoma cells leading to the cell death might be an important pharmaceutic target finding for glioblastoma cell survival." (PMID 34357080, 2021). "Furthermore, unexpected data are that the Smad1 gene knockdown could lead to the cell death of human LN18 glioblastoma cells." (PMID 34357080, 2021). "Moreover, we also had a surprising Smad1 data in glioblastoma cell survival." (PMID 34357080, 2021).
glioblastoma (continued). "Indeed, exposure of glioblastoma stem-like cells to recombinant BMP7 in vitro increased SMAD1/5/8 phosphorylation, inhibited cell proliferation, stimulated glioblastoma differentiation, decreased neurosphere formation and attenuated expression of the stem-like genes Nanog, SOX2, Nestin and Olig2." (PMID 29799477, 2018). "Because Smad1/5 can be activated by both TGF-β and BMP ligands, we sought to ascertain the contribution of TGF-β signalling to lattice formation in glioblastoma." (PMID 39724753, 2024). "The endothelialisation of glioblastoma tumour cells, however, requires the expansion of the TGF-β signalling for the activation of the intracellular effectors Smad1/5 downstream ALK1." (PMID 39724753, 2024). "VEGF was released in glioblastoma by TGFβ regulation, leading to the phosphorylation of SMAD2, SMAD3, and SMAD1/5/8 and increased VEGF release." (PMID 34067437, 2021). "Supporting this idea, an interaction of SNAIL1 with SMAD1 and SMAD4 was recently shown in glioblastoma." (PMID 32326239, 2020). "Altogether, these results demonstrate that glioblastoma progression is driven by the integration of tumour cells in the vasculature, which relies on the capacity of cancer cells to undergo endothelialisation in response to TGF-β-Smad1/5 signaling activation." (PMID 39724753, 2024). "Demonstrating the role played by TGF-β-Smad1/5 signaling in this process, knockdown of the TGF-β type I receptor ALK1 or overexpression of the inhibitory Smad6 reduced endothelialisation and impaired glioblastoma progression." (PMID 39724753, 2024). "The present study has found an autocrine BMP7 effect on glioblastoma transmigration and migration in human LN18 glioblastoma cells through Smad5, but not Smad1, and p75NTR signaling pathway." (PMID 34357080, 2021). "In our previous study, we detected decreased expression of phospho-Smad1/5/8 and its upstream signaling molecule, bone morphogenetic protein receptor IB subunit (BMPR-IB), in certain glioblastoma tissues, unlike normal brain tissues." (PMID 22650359, 2012). "Our previous studies have shown that overexpression of BMPR-IB can arrest the growth of glioblastoma cells in which there were almost no expression of BMPR-IB and bring about their differentiation by the activation of Smad1 and up-regulation of p21 and p27kip1 in vitro and in vivo." (PMID 26908439, 2016).
liver fibrosis (9 papers, 2020 to 2025). "Studies have shown that TGFβ1 crosstalks with BMP7, BMP9, and SMAD1/5/8, all of which can affect liver fibrosis 45-47." (PMID 33754025, 2021). "In line with this, it has been shown in several studies that endoglin can enhance TGF-β1-induced Smad1/5 and/or Smad2/3 phosphorylation in scleroderma fibroblasts, liver fibrosis, and cardiac fibrosis." (PMID 33081058, 2020). "SMAD1 activation is also involved in liver fibrosis and systemic sclerosis 53-55." (PMID 34158869, 2021). "Phosphorylated Smad1/5/8 competes with phosphorylated Smad2/3 to bind Smad4 to suppress the transcription of liver fibrosis-related genes, and BMP-7 promotes the phosphorylation of Smad1/5/8 in hepatic stellate cells." (PMID 36389166, 2022). "In a mouse model, hepatocytes lacking Smad1/5/8 exhibited severe tissue iron loading and liver fibrosis." (PMID 39199400, 2024).
Infertility (8 papers, 2012 to 2024). "A 6-month fertility trial indicated that conditional deletion of Smad1 resulted in normal fertility, conditional deletion of Smad5 resulted in subfertility, whereas double conditional deletion of Smad1/5 resulted in infertility." (PMID 34099644, 2021). "Double conditional deletion of SMAD1/5 led to infertility, whereas single conditional deletion of SMAD1 or SMAD5 resulted in normal fertility or subfertility, respectively." (PMID 34099644, 2021). "Conditional deletion of SMAD1/5/4 exclusively in the cells from mesenchymal lineage (including uterine stroma) using anti-Mullerian hormone type 2 receptor cre (Amhr2-cre) results in infertility with defective decidualization." (PMID 38536963, 2024). "SMAD1 knockout mice exhibited embryonic death at E10.5 to E11.5, no or very little formation of primordial germ cells, decreased steroid hormone production, ovulation dysfunction and infertility." (PMID 36553573, 2022). "Female mice with SMAD1/5 deletion showed endometrial defects leading to the development of cystic endometrial glands, endometrial epithelial hyperplasia during the implantation window and impaired apical–basal transformation, preventing embryo implantation and leading to infertility." (PMID 36553573, 2022). "Female mice with SMAD1/5 deletion display endometrial defects that result in the development of cystic endometrial glands, a hyperproliferative endometrial epithelium during the window of implantation, and impaired apicobasal transformation that prevents embryo implantation and leads to infertility." (PMID 34099644, 2021). "When mice are experimentally rendered infertile by cyclophosphamide, treatment with conditioned medium and PRP was able to boost expression of ‘mothers against decapentaplegic’ homologs 1 and 2 (SMAD1, SMAD2), growth differentiation factor-9 (GDF9), and bone morphogenetic protein-15 (BMP15)." (PMID 37505061, 2023). "To rule out any potential embryonic contribution to the infertility phenotype of the Smad1/5 cKO and Acvr2a cKO mutant mice, we also transferred embryos derived from Smad1/5 cKO and Acvr2a cKO donors to the uteri of WT recipients." (PMID 34099644, 2021). "Moreover, conditional double deletion of SMAD1 and SMAD5 or triple deletion of SMAD1, SMAD5, SMAD8 led to infertility and granulosa cell tumor development in mice." (PMID 34069790, 2021).
myocardial infarction (8 papers, 2015 to 2025). Gross necrosis of the myocardium, as a result of interruption of the blood supply to the area, as in coronary thrombosis. "Administration of miR-26a-5p inhibitor to mice increases SMAD1 expression, induces angiogenesis, reduces myocardial infarct size, and improves heart function." (PMID 31086410, 2019). "For instance, following myocardial infarction, BMP4/Smad1 signaling promotes cardiomyocyte apoptosis through ROS-dependent pathways, and inhibition of BMP signaling confers protection against acute myocardial infarction." (PMID 26317208, 2015). "The results showed that the content of BMP3b and phosphorylation of Smad1/5 in the hearts of mice increased after myocardial infarction, but the difference was not statistically significant." (PMID 41207916, 2025). "In this study, we ligated the left anterior descending coronary artery of mice to simulate myocardial infarction in patients, considering the possibility of BAT activation in AMI injury and the role of BAT and the BMP3b/Smad1/5 signalling pathway in alleviating myocardial injury by EA." (PMID 41207916, 2025). "Some researchers have shown that miR-26a could inhibit the activity of angiogenesis in liver cancer, acute myocardial infarction, and diabetes by directly targeting signaling pathways, such as hepatocyte growth factor-cMet pathway and BMP/Smad1 pathway." (PMID 31730486, 2019).
osteoarthritis (8 papers, 2015 to 2025). A noninflammatory degenerative joint disease occurring chiefly in older persons, characterized by degeneration of the articular cartilage, hypertrophy of bone at the margins and changes in the synovial membrane. "High levels of TGF-β, as seen in osteoarthritis, cause preferential activation of the Smad1/5/8 pathway, which results in chondrocyte activation and hypertrophy." (PMID 41019141, 2025). "Of interest, a recent study showed collagen II suppresses articular chondrocyte hypertrophy and osteoarthritis progression by promoting β1-integrin-SMAD1 interaction, thus inhibiting BMP-SMAD1-mediated chondrocyte hypertrophy." (PMID 32984311, 2020). "Microarray analysis data of ARV infected cells and σB transfected cells were validated by using primers of 4 important candidate genes (SPP1, BMP2, SMAD1 and IL1B) that were involved in osteoarthritis pathway." (PMID 29731966, 2018). "Furthermore, in studies on osteoarthritis, an age-related shift in the ALK1/ALK5 ratio altered TGF-β downstream signals by favoring Smad1/5/8 over Smad2/3." (PMID 31658594, 2019). "In osteoarthritis, the material properties of the cartilage ECM deteriorate as chondrocytes inappropriately shift the balance from canonical (Alk5/Smad2/3) to non-canonical (Alk1/Smad1/5/8) TβRI signaling." (PMID 26652004, 2015).